IL10 (interleukin 10)
Diseases named in the same sentence as IL10 in open-access papers (continued):
Sharing a sentence is not in itself a finding about the gene and the disease.
colitis (continued). "After mice with TNBS-induced colitis were treated by intragastric administration of ginsenoside Rb1, the levels of pro-inflammatory cytokines (TNF-α, IL-1β, and IL-6) declined, while the levels of anti-inflammatory cytokines (IL-10) increased." (PMID 33462754, 2021). "Consistent with the known uneven disease penetrance in mice lacking IL-10 (Jax), neither the IL-10-/- nor IL-10 cKO mice used for these experiments had developed colitis, thereby reducing confounding factors associated with T cell function." (PMID 33617447, 2021). "Additionally, L. reuteri is able to elevate IL‐10 and suppress inflammation in a TNBS model of colitis." (PMID 33463911, 2021). "Lack of negative regulation by IL-10 leads to NLRP3 overactivation in Il10−/− mice that develop spontaneous colitis." (PMID 34344313, 2021). "In our SPF colony of IL-10−/− mice, colonization with H. hepaticus rapidly triggers the development of typhlocolitis, while no colitis is seen in wild-type animals carrying H. hepaticus." (PMID 34126769, 2021). "We further demonstrated that administration of the rTsSp without the additional adjuvant before the induction of DSS-induced colitis reduced the severity of intestinal inflammation and the disease index; it suppressed macrophage infiltration, reduced TNF-α secretion, and induced IL-10 expression." (PMID 33995396, 2021). "We confirmed that wild-type mice did not develop signs of intestinal inflammation, regardless of H. hepaticus colonization status, whereas IL-10−/− mice colonized with H. hepaticus did develop colitis." (PMID 34126769, 2021). "CX3CR1+ macrophage-derived IL-10 is not required to tame colitis in mice; however, IL-10R expressed by macrophages is essential to prevent fulminant enterocolitis with upregulated pro-inflammatory genes, including Nos2, Il23a, Ccl5, Ccr7, and Saa3." (PMID 33562334, 2021). "In experimental settings (possibly due to pathogenic Th17 cells (pTh17)), barrier perturbation is further increased during the co-blockade of IL-10 signaling or ICOS (Inducible T-cell COStimulator) signaling, resulting in higher intestinal toxicity resembling early signs of colitis." (PMID 33401586, 2021). "This is similar to the report that NOD2 signaling contributes to intestinal inflammation and the development of colitis in patients with inflammatory bowel disease in the absence of IL-10 signaling." (PMID 34768828, 2021). "However, oral gavage of NK210 and/or NK219 suppressed cyclophosphamide-induced colitis: they increased IFN-γ, TNF-α, and IL-10 expression, but decreased myeloperoxidase activity and IFN-γ to IL-10 and TNF-α to IL-10 expression ratios in the colon." (PMID 34667205, 2021). "Although Il10−/− mice are not defective in mucin production, but have its defective loose quality that makes mice suffer from spontaneous colitis." (PMID 34124086, 2021). "For instance, it has been shown that mice lacking IL-10 develop spontaneous colitis and that pro-inflammatory Th17 cells can be directly controlled by IL-10." (PMID 34831261, 2021). "Supplementation of taxifolin (a natural antioxidant polyphenol) significantly inhibited the NF-κB signalling pathway and significantly increased the secretions of IL-10, secretory immunoglobulin A, superoxide dismutase, and immunoglobulins (IgA, IgG, and IgM) in DSS-induced colitis mice." (PMID 34067016, 2021). "Furthermore, while experimental colitis upregulated inflammatory genes in the colon, including Tnfa, Il6 and Ifng, UC patients also upregulated IL17A and IL10, followed by a slight increase in IL4 and mevalonate kinase (MVK) expression." (PMID 34434187, 2021). "ET failed to alleviate colitis when OVA TCR enriched T cells were derived from IL-10−/− or CD4-dnTGFBRII mice." (PMID 33717186, 2021). "In experimental colitis, MCHR1 antagonist reduced colonic inflammation, probably by blocking IL10 upregulation, suggesting that inhibition of MCH/MCHR1 signaling could be a novel anti-inflammatory therapeutic approach." (PMID 34912333, 2021).
colitis (continued). "DSS exposure induced colon Il33 expression significantly compared to untreated mice, suggesting that IL-10 is not required for Il33 induction during colitis." (PMID 33953267, 2021). "IL-10 treatment was only efficient in initial colitis but not in established IBD of the mouse model." (PMID 34421890, 2021). "This study showed that L. plantarum ZS62 could regulate IL-1β, IL-12, TNF-α, IL-10, COX-2, iNOS, NF-κB p65, and IκB-α expression in the colon tissues of mice with enteritis to inhibit colitis." (PMID 34745426, 2021). "Moreover, oral gavage of ampicillin induced colitis: it increased colon shortening, myeloperoxidase activity, and IFN-γ and TNF-α expression and reduced IL-10 expression in the colon." (PMID 34667205, 2021). "However, DPA induced a stronger increase in anti-inflammatory cytokine IL-10 levels than EPA and DHA in a colitis model induced by dextran sulphate sodium." (PMID 34822458, 2021). "IL-10−/− mice challenged with C. difficile spores in the absence of H. hepaticus-triggered colitis or antibiotic pretreatment were resistant to C. difficile colonization." (PMID 34126769, 2021). "The transfer of Il-10−/− CD11b+ B cells inhibited colitis, suggesting that IL-10 is not essential for CD11b+ B cell regulatory function." (PMID 34804004, 2021). "The cytokine production profile in mesenteric lymph nodes (MLN) indicated that secretion of the inflammatory cytokine (IL-22) and anti-inflammatory/regulatory cytokine (IL-10) was significantly upregulated and downregulated, respectively, in DSS colitis mice compared with control mice." (PMID 34681392, 2021). "For example, when conventional IL-10-deficient mice are administered AOM, they develop colitis and carcinomas in the colon, while axenic AOM-IL-10−/− mice are tumor-free and without histological damage." (PMID 34068653, 2021). "Colon Il33 was induced in WT and Il10−/− mice exposed to DSS, but not in unchallenged Il10−/− mice with colitis." (PMID 33953267, 2021). "Further, FMT significantly increases MHC-II–dependent secretion of IL-10 by CD4+ T cells and is useful for the treatment of experimental colitis, while also reducing the ability of dendritic cells, monocytes, and macrophages to present MHC-II–dependent bacterial antigens to colonic T cells." (PMID 32318067, 2020). "Besides the IL-10–/– mice, The most commonly used models include DSS (dextran sulfate sodium)-induced colitis, TNBS (2,4,6-trinitrobenzenesulfonic acid)-induced colitis, oxalazone-induced colitis, and T cell adoptive transfer colitis." (PMID 32634481, 2020). "In addition, the alteration of pro- and anti-inflammatory cytokine levels, such as IL-6, IL-1β, TNF-α, and IL-10, in the serum of the DSS-induced colitis mice were determined by ELISA." (PMID 33391246, 2020). "Based on this finding, we concurrently applied mSjci and DSS to mice and found that mSjci exerted protective effects on mice with DSS-induced colitis by suppressing proinflammatory Th1 cytokine (IFN-γ) production and promoting regulatory cytokine (IL-10) secretion." (PMID 33469451, 2020). "However, the administration of LpEVs attenuated the increased expression of pro-inflammatory cytokines while further increasing the expression of IL-10 and TGFβ in DSS-induced colitis mice." (PMID 32123288, 2020). "Dex treatment strongly upregulated the expression of the cytokines TNFα, IL-1β and IL-6 but not IL-10 in the course of DSS colitis compared with that in the control group." (PMID 32290362, 2020). "Littermate control IL10+/− or uninfected IL10−/− mice did not developed major signs of colitis or tumorigenesis." (PMID 32286276, 2020). "Moreover, in colitis, the intestinal microbiota and specific microbial components activate downstream MyD88 and PI3K pathways through TLR2, to activate IL-10–producing B cells." (PMID 32318067, 2020).
colitis (continued). "First, our animal studies focused on the DSS-induced model of colitis-associated colorectal cancer, and we have not yet explored the impact of TWD in the Il10-/- mouse model of spontaneous colonic inflammation." (PMID 32093192, 2020). "In summary, our findings provide evidence showing that mSjci could attenuate DSS-induced colitis in mice by inhibiting the production of IFN-γ, promoting the expression of IL-10 and enhancing the population of CD4+CD25+ Treg cells." (PMID 33469451, 2020). "It was also found that mice that the lack of IL-10 or IL-10R are sensitive to colitis, largely due to the promotion of IL-1 production." (PMID 32831636, 2020). "Littermate control IL10+/− mice, which did not develop colitis or colon polyps after infection, also did not develop dysbiosis." (PMID 32286276, 2020). "In another study involving colitis, it was shown that activation of CB2 by JTE907 promotes the differentiation of Th0 cells into the Treg cell phenotype, which was characterized by the expression of FoxP3, TGF-β, and IL-10." (PMID 32612530, 2020). "Moreover, oral administration of TUDCA and 4-PBA reduced ER stress in Il10-/- mice and DSS-induced colitis in P58IPK-/- and Atf6-/- mice." (PMID 33324392, 2020). "A previous study showed that CD4+ T cells in IL-10-/- mice produced similar IFNγ levels compared to CD4+ T cells in IL-23-/-IL-10-/- mice in spontaneous model of colitis, indicating normal Th1 response in IL-23- and IL-10-deficient environment." (PMID 33488580, 2020). "Both in the DSS-induced colitis model and in the colitis model induced by adoptive transfer of naive T cells, BDNs prevented intestinal damage and determined a reduction in the expression of TNF-α, IL-17A, and IFN-γ and an increased expression of IL-10." (PMID 33336066, 2020). "Danese and coworkers previously showed that treatment with the non‐RGD‐based peptide ATN161, which blocks both αvβ3 and α5β1 integrins, effectively decreased angiogenesis and improved colitis in the IL‐10−/− mouse model but not in the DSS‐induced model." (PMID 31793743, 2020). "Furthermore, studies with mice models of colitis have showed that exogenously added GABA attenuated the colitis-induced TNF-α increase and instead increased the production of the anti-inflammatory cytokine IL-10." (PMID 33066564, 2020). "Supplementation of taxifolin significantly inhibited the secretions of tumor necrosis factor-α, interleukin (IL)-1β, and IL-6 and significantly increased the secretions of IL-10, secretory immunoglobulin A, superoxide dismutase, and immunoglobulins (IgA, IgG, and IgM) in DSS-induced colitis mice." (PMID 33664740, 2020). "Interestingly, high levels of TMA/TMAO have been found in IBD patients and in the animal models of colitis DSS and IL-10−/−." (PMID 32429195, 2020). "Oral treatments with the compounds significantly suppressed TNBS-induced expressions of IL-10, in addition to TNF-α, IL-6, and IL-1β in colon tissues, indicating that an anti-colitis activity of the compounds led to the resolution phase of TNBS-induced inflammation." (PMID 31619080, 2020). "Il10-/- mice that are also TNF-deficient (Tnf-/-Il10-/-; termed “T/I” mice) uniformly develop moderate to severe colitis by age 4–6 weeks without the need for exogenous triggering." (PMID 32941525, 2020). "Further results of this study also showed that while IL-10 and TGF-β play protective roles in DSS-induced colitis, the protection provided by male S. mansoni cercariae is independent of these cytokines, since treatment with anti-IL-10 and anti-TGFβ did not result in increased symptom scores." (PMID 32903582, 2020). "Based on the important roles of IL‐10 in the development of normal mucosal immunity, researchers have investigated the potential for exosomes derived from DCs treated with IL‐10 to suppress TNBS‐induced colitis." (PMID 32410383, 2020).
colitis (continued). "On the other hand, infection of 4-week-old IL10−/− mice with Citrobacter rodentium (C. rodentium) did not lead to colitis or polyp formation in the colon." (PMID 32286276, 2020). "Accordingly, there was no significant change in the expression of GATA3 or IL-10 in the DSS-induced colitis group." (PMID 32034203, 2020). "However, the treatment of colitis mice with ED amino acids effectively eliminated the DSS-mediated increase in IL-6 and reduction in IL-10 protein levels in the serum." (PMID 32855978, 2020). "In contrast, addition of B. vulgatus is not sufficient to induce colitis in IL-10-/- mice, which suggested that resident enteric bacteria are necessary for immune activation and this development of spontaneous colitis in this model." (PMID 33537028, 2020). "Knock out of IL-10 induces colitis in mice, which is dependent on the microbiota since germ-free mice do not develop colitis." (PMID 33178196, 2020). "IL10, which has been shown to downregulate IFNγ expression and to protect from colitis was not increased in Tbet knockout mice." (PMID 31572375, 2019). "Strikingly, mice deficient for Maf in Treg alone (MafΔTreg mice) did not develop colitis and demonstrated normal levels of IL-10 in their colon." (PMID 30992496, 2019). "Their assessment showed that CBG attenuated the colitis by improving SOD activity and NO production, and indicated normalized levels (towards the control) of interleukin-1β, interleukin-10 and interferon-γ, as well as reduced ROS formation in intestinal epithelial cells." (PMID 31027169, 2019). "Furthermore, a member of the Bacteroidetes family, gut inhabitant Bacteroides fragilis, was shown to protect mice from experimental colitis, mediated by polysaccharide A (PSA) possibly through IL-10 induction." (PMID 31781154, 2019). "Recent studies of an IL10-/- mouse model of IBD have identified NLRP6 as an important inhibitor of spontaneous colitis, whereas a lack of NLRP6 leads to the enrichment of Akkermansia muciniphila." (PMID 30971953, 2019). "We utilized tissue sections from wild type (WT) mice and IL-10 deficient mice (IL-10KO) with and without acute DSS colitis to examine E-cadherin expression." (PMID 30809073, 2019). "However, B cells may also dampen immune responses through the secretion of IL10 (so-called regulatory B cells) and both splenic B cells and B cells from the peritoneal cavity have been shown to control inflammatory T cell responses in chemically-induced models of colitis though this pathway." (PMID 31708923, 2019). "In a TNBS rat colitis model, Escherichia coli Nissle 1917, at low doses of the strain (107cfu/day), has been demonstrated to reduce the disease activity index, colonic MPO activity, and TNF‐α levels and to increase IL‐10 expression." (PMID 31572604, 2019). "In addition, chronic exposure to IL-12 was reported to rather induce suppressive IL-10-production in CD4+ T cells, which further decreases the possible involvement of IL-12 in colitis." (PMID 30653608, 2019). "The absence of colitis onset is associated with a very limited accumulation of TH17 cells and normal expression level of IL-10 in the colon." (PMID 30992496, 2019). "In line with this, we have shown in a previous study that genes that produce two colitis-relevant structures in E. faecalis are not transcriptionally regulated in inflamed monoassociated IL-10−/− mice." (PMID 31281321, 2019). "In IL-10-/-mice, various experimental regimens including piroxicam, 2,4,6-trinitrobenzenesulfonic acid (TNBS) or dextran sulfate sodium (DSS), respectively were used for promoting colitis; colitis was induced with DSS in FVB mice." (PMID 31534535, 2019). "Our data that ER stress reduces the sensitivity to IL-10 nicely corresponds with previous findings that show that lack of IL-10 induces colitis." (PMID 31227842, 2019).
colitis (continued). "While AOM is genotoxic to colonic epithelial cells and DSS-induced colitis, induction of colon carcinogenesis did not promote pro-inflammatory markers; however, reduced IL-10 content was observed in the colon." (PMID 30626010, 2019). "Female IL-10−/− mice were monitored for colitis development for 15 weeks: at weaning (day 30) (no colitis), 15 weeks post-weaning (day 135) (severe colitis), and at an intermediate time point (day 93) (mild colitis)." (PMID 30774653, 2019). "Impressively, the number of cLP IL-10-producing B cells from 8–10 week old PI3KδD910A; Il10eGFP mice, which have not yet developed colitis, were lower by 8-fold compared with those in WT; Il10eGFP mice." (PMID 31546615, 2019). "Our results show that genetically engineered mice such as IL-10-/- mice, although prone to developing spontaneous colitis, failed to develop sustained chronic colitis with piroxicam promotion for dual-selectin targeted USMI purposes." (PMID 31534535, 2019). "DSS-colitis model mice produced high levels of the proinflammatory cytokines IL-1β, IL-6 and TNF-α, and B. adolescentis IF1-03 mice produced lower IL-1β, IL-6 and TNF-α, and elevated levels of the anti-inflammatory IL-10, compared to the DSS-colitis model and B. adolescentis IF1-11 protection mice." (PMID 30987344, 2019). "As evidenced in a DSS-induced colitis model, IPA protects lipopolysaccharide (LPS)-challenged mice by activating AhR to promote interleukin-10 (IL-10, an anti-inflammatory cytokine) production while suppressing gene expression of TNF-α, a proinflammatory cytokine." (PMID 30691236, 2019). "Moreover, after giving oral L. acidophilus to colitis mice induced by dextran sulfate sodium (DSS), they found that not only Treg and IL-10 were increased but also IL-17 was decreased in the spleen." (PMID 31143780, 2019). "However, treatment of DSS + CD-induced colitis mice with PWS produces a reduction in the level of IL-1β and an increase in the expression of both IL-10 and TGF-β in the colonic tissue." (PMID 31888274, 2019). "Significantly lower number of IL-10-, IL-4- and TGF-β-producing M2 macrophages infiltrated colons of DSS-treated Gal-3−/− animals 28 days after initial administration of DSS, which resulted in aggravation of DSS-induced colitis." (PMID 31336879, 2019). "It appears that mice received S.obvelata like some nematodes can simulated tolerogenic-DCs (tDCs) and macrophages boosted Treg cells that secreted regulatory cytokines, such as IL-10 and TGF-β72,73, and inhibited the Th1- and Th17-related cytokines that leaded to attenuation of experimental colitis." (PMID 31836772, 2019). "In IL-10−/− mice colonized with the SIHUMI consortium, we observed a gradient of colitis severity." (PMID 31281321, 2019). "Thus, we focused on the immunoregulation of ERCs on the balance of the B-cell system in colitis, especially IL-10-competent B cells, and found that ERC-treated mice showed increased IL-10+ B cells in the spleen." (PMID 29784012, 2018). "NC101, a commensal E. coli strain isolated from healthy mice, also exacerbated colitis when monoassociated with germ-free IL-10−/− mice but not in wild-type control animals." (PMID 30356663, 2018). "Mice lacking IL-10 or IL-10R are sensitive to colitis because IL-10 is a significant anti-inflammatory cytokine that represses the production of proinflammatory mediators." (PMID 29682569, 2018). "Chitin treatment increased chitinase-3-like protein-1, enabling chitin digestion and the generation of small sized chitin particles that induced IL-10 production via PPARg, NOD-2, and TLR-8 sensing, promoting the attenuation of colitis and C. glabrata elimination." (PMID 29463799, 2018). "Although this strategy profoundly diminished the pool of pDCs in Il10−/− mice, we did not detect any major impact on the development of colitis." (PMID 30410494, 2018).